BAMBI (BMP and activin membrane bound inhibitor)
Diseases named in the same sentence as BAMBI in open-access papers (continued):
Sharing a sentence is not in itself a finding about the gene and the disease.
viral infection (3 papers, 2012 to 2024). "In vitro studies of human biliary epithelial cells showed downregulation of BAMBI in response to poly (I:C), a viral dsRNA analog, suggesting that dsRNA virus infection could lead to loss of cell-to-cell adhesion and epithelial mesenchymal transition (EMT)." (PMID 22509103, 2012). "In contrast, α-cell-specific transcripts including GCG, ARX, BAMBI, DPP4, and POU6F2 were not affected by infection, which corresponded with our observation that viral infection was infrequent in α cells." (PMID 32093375, 2020).
chronic obstructive pulmonary disease (2 papers, 2016 to 2019). A chronic and progressive lung disorder characterized by the loss of elasticity of the bronchial tree and the air sacs, destruction of the air sacs wall, thickening of the bronchial wall, and mucous accumulation in the bronchial tree. "Furthermore, strong upregulation of BAMBI expression following in vitro infection of chronic obstructive pulmonary disease (COPD) lung tissue has been demonstrated." (PMID 27549738, 2016).
gastric cancer (2 papers, 2016 to 2024). A primary or metastatic malignant neoplasm involving the stomach. "BAMBI is reportedly linked to the development and progression of various human cancers, including colorectal cancer, HCC, lung cancer, bladder cancer, gastric cancer, and gliomas." (PMID 39684424, 2024). "The knockdown of BAMBI suppresses metastasis in gastric cancer cells by inhibiting β-catenin and TGF-β." (PMID 39684424, 2024).
Hepatic steatosis (2 papers, 2021 to 2023). Steatosis is a term used to denote lipid accumulation within hepatocytes. "Altogether, these data suggested that loss of BAMBI in adipocyte exacerbated HFD-induced liver steatosis in part due to increased fatty acid uptake and lipogenesis." (PMID 33158991, 2021). "The BAMBI null mice had liver steatosis and were glucose-intolerant, insulin-resistant, and hypercholesterolemic." (PMID 36834884, 2023). "One study reported BAMBI protein to be low in human liver steatosis." (PMID 36834884, 2023). "Whether BAMBI is already regulated in liver steatosis has not been sufficiently studied so far." (PMID 36834884, 2023).
liver disease (2 papers, 2023 to 2024). "This review aims to summarize the current knowledge about the expression and function of BAMBI in liver diseases." (PMID 36834884, 2023). "However, hepatic BAMBI expression in relation to underlying liver diseases has not been evaluated as far as we know." (PMID 39457709, 2024). "Data in the human liver are limited, and expression of hepatic BAMBI protein in HBV, HCV, and ethanol-related liver diseases has hardly been analyzed." (PMID 36834884, 2023).
multiple myeloma (2 papers, 2016 to 2023). "We selected genes (ARHGAP26, MYH10, PMP2, RFX8, BAMBI, CLEC12b) with significant changes in methylation level to validate their expression using qRT-PCR in U266 myeloma cells." (PMID 38201971, 2023). "BAMBI has been found to be part of a gene signature overexpressed in multiple myeloma and pluripotent stem cells." (PMID 27689402, 2016).
non-small cell lung carcinoma (2 papers, 2018 to 2025). A group of at least three distinct histological types of lung cancer, including non-small cell squamous cell carcinoma, adenocarcinoma, and large cell carcinoma. "Previous studies indicated that BAMBI downregulation can enhance TGF-β signaling, promoting EMT in non-small cell lung cancer, and contributing to platinum resistance in epithelial ovarian cancer." (PMID 41395597, 2025).
pancreatic cancer (2 papers, 2021 to 2024). "BAMBI was also highly expressed in pancreatic cancer by the TGF-beta pathway." (PMID 34188683, 2021). "Of note, a study from a decade ago proposed BAMBI to promote pancreatic tumor metastasis in TGF-intact tumors; however, there is no report of its mechanism." (PMID 37950093, 2024).
airway hyperresponsiveness (1 paper, 2020). "BAMBI knock out mice model of asthma demonstrated significantly reduced airway hyperresponsiveness, pulmonary inflammation, broncho-alveolar lavage fluid (BALF) eosinophil count, as well as diminished IL-4, IL-5, IL-13 and IL-6." (PMID 32900903, 2020).
asthma (1 paper, 2020). "Drug (entinostat, BMS-345541) and genetic perturbagens (KLF6, BCL10, INFB1 and BAMBI) negatively connected to disease at multi-tissue level could potentially repurposed for treating asthma." (PMID 32900903, 2020). "In addition to asthma, the enhanced plasma BAMBI level in COPD positively correlated with the increased plasma TGF-β1 levels and peripheral Th17/Treg ratio indicating the significance of TGF-beta/BAMBI pathway in pulmonary disease." (PMID 32900903, 2020).
Autoimmunity (1 paper, 2018). The occurrence of an immune reaction against the organism's own cells or tissues. "Selective reduction in TGF-β1 and enhanced BAMBI expression may be associated with the increase in autoimmunity in COPD." (PMID 29289685, 2018).
colon adenocarcinoma (1 paper, 2020). "BAMBI, on the other hand, showed weak co-expression in colon adenocarcinoma and ovarian serous surface papillary carcinoma." (PMID 31973134, 2020).
colorectal tumor (1 paper, 2020). "For example, TGFβ1 causes up-regulation of BAMBI mRNA and protein in HEPG2 cells via the P-SMAD2/3-4 transcriptional pathway, and stimulation of WNT/β-catenin signaling increases BAMBI in colorectal tumor cells." (PMID 32373617, 2020).
cyst (1 paper, 2024). A sac-like closed membranous structure that may be empty or contain fluid or amorphous material. "HIF1α upregulation in hypoxia was documented to activate the TGFβ-pathway via upregulation of BAMBI eventually leading to loss of epithelial polarity and HIF1αKD rescued normal cyst formation in hypoxic conditions." (PMID 38802496, 2024).
fibrosis (1 paper, 2023). the formation of excess fibrous connective tissue in an organ or tissue in a reparative or reactive process. "In conclusion, BAMBI regulates signaling pathways involved in hepatocarcinogenesis, liver fibrosis, and inflammation." (PMID 36834884, 2023).
gestational diabetes mellitus (1 paper, 2023). "METTL14 was found to be reduced in the placentas of mothers with gestational diabetes mellitus, which in turn decreased BAMBI m6A levels, thereby causing a lower BAMBI expression level." (PMID 36894952, 2023).
glomerular disease (1 paper, 2010). "This may point towards novel roles of BAMBI for endothelial function in glomerular disease." (PMID 20886049, 2010).
Glucose intolerance (1 paper, 2021). Glucose intolerance (GI) can be defined as dysglycemia that comprises both prediabetes and diabetes. "Fortunately, BAMBI AKO mice exhibited glucose intolerance and insulin resistance compared with BAMBI-Flox mice." (PMID 33158991, 2021).
heart malformations (1 paper, 2021). "Furthermore, in two non-consanguineous unrelated individuals with heart malformations, among other disorders, microdeletions at 10p11.23-p12.1 (overlapping ARMC4, MPP7, BAMBI and WAC) were identified." (PMID 34324492, 2021).
Impaired glucose tolerance (1 paper, 2021). An abnormal resistance to glucose, i.e., a reduction in the ability to maintain glucose levels in the blood stream within normal limits following oral or intravenous administration of glucose. "In the present study, decreased adipose BAMBI expression caused impaired glucose tolerance and insulin resistance in HFD-fed mice, but not in CD-fed mice (data not shown)." (PMID 33158991, 2021).
Insulin resistance (1 paper, 2021). Increased resistance towards insulin, that is, diminished effectiveness of insulin in reducing blood glucose levels. "In our study, BAMBI deficiency worsens insulin resistance and inflammatory infiltration in adipose tissue." (PMID 33158991, 2021). "Moreover, mice with adipocytes deficient in BAMBI show an increased onset of insulin resistance with upregulated adipose tissue inflammation." (PMID 33158991, 2021).
keloid (1 paper, 2023). An irregularly shaped, elevated mark on the skin caused by deposits of excessive amounts of collagen during wound healing. "As prolonged TGF-β signaling is normally associated with an excessive scar or keloid formation, modulation of BAMBI in experimental wound healing so far addressed the potential therapeutic effects of BAMBI." (PMID 37626905, 2023). "For example, BAMBI has been shown to inhibit skin fibrosis in keloids by suppressing TGF-β1-induced hyper normal fibroblast proliferation and excessive type I collagen accumulation." (PMID 37626905, 2023).
lymphoma (1 paper, 2026). A malignant (clonal) proliferation of B- lymphocytes or T- lymphocytes which involves the lymph nodes, bone marrow and/or extranodal sites. "Collectively, these findings identified the BAMBI‐Wnt‐TGF‐β axis as a novel pathway by which HBV results in the CD4+ T cell exhaustion in lymphoma." (PMID 41492119, 2026).
mesothelioma (1 paper, 2022). A usually malignant and aggressive neoplasm of the mesothelium which is often associated with exposure to asbestos. "Finally, we report that elevated BAMBI expression is associated with poor clinical outcomes in mesothelioma patients, highlighting BAMBI as a potential molecular target for treatment." (PMID 36109807, 2022). "Notably that elevated BAMBI mRNA expression was associated with shorter survival of mesothelioma patients." (PMID 36109807, 2022). "Further, in silico analysis revealed that elevated BAMBI expression is associated with reduced survival rates in mesothelioma patient, suggesting that BAMBI may be an effective molecular target for MM therapy." (PMID 36109807, 2022). "Our findings suggest that BAMBI is regulated by CTGF promoting mesothelioma growth by driving cell cycle progression." (PMID 36109807, 2022). "In mesothelioma and mesothelial cells as well, BAMBI immunofluorescence staining was observed mainly in the cytosol and to a lesser extent in the cell membrane, suggesting additional signaling functions aside from regulation of TGF-β/BMP signaling by acting as a pseudoreceptor." (PMID 36109807, 2022). "RT-qPCR confirmed that CTGF knockdown reduced BAMBI expression in both Y-MESO-14 and Y-MESO-27 cells as well as in four of the five other mesothelioma cell lines subjected to CTGF knockdown." (PMID 36109807, 2022). "To investigate the mechanism of cell growth regulation by CTGF in mesothelioma cells, we performed cDNA microarray analysis using Y-MESO-27 cells and found that BAMBI gene expression was suppressed by siRNA CTGF (data not shown)." (PMID 36109807, 2022).
Myocardial fibrosis (1 paper, 2024). "Bone morphogenetic protein and activin membrane-bound inhibitor (BAMBI) have been shown to alleviate myocardial fibrosis by inhibiting the transforming growth factor β1 (TGF-β1) signaling pathway." (PMID 38807415, 2024).
Niemann Pick type C disease (1 paper, 2023). "Low expression of BAMBI mRNA in HSCs of mice with Niemann Pick type C disease also suggests a role for lipids as regulators of BAMBI." (PMID 36834884, 2023).
ocular infection (1 paper, 2012). "We also identified other genes, including IDO1 and BAMBI, that may influence the RPE and therefore outer blood-retinal barrier integrity during ocular infection and inflammation, or are associated with degeneration, as seen for example in aging." (PMID 22509103, 2012).
prion disease (1 paper, 2020). A transmissible disease that is caused by a protein that is able to induce abnormal folding of normal cellular proteins, leading to characteristic spongiform brain changes, which are associated with neuronal loss without an inflammatory response. "Further research is still required to elucidate the molecular pathways in which BAMBI and CHGA could be participating in prion disease-related conditions." (PMID 32370154, 2020).
prostate carcinoma (1 paper, 2025). A carcinoma that arises from epithelial cells of the prostate gland. "miR-93-5p, an effector of the TGF-β signalling pathway in prostate cancer, has been predicted to act on and bind to BAMBI, consequently inhibiting BAMBI expression and activating TGF-β signalling." (PMID 40566602, 2025).
pulmonary fibrosis (1 paper, 2019). Chronic progressive interstitial lung disorder characterized by the replacement of the lung tissue by connective tissue, leading to progressive dyspnea, respiratory failure, or right heart failure. "BAMBI has been reported to extensively participate in immunological diseases, such as pulmonary fibrosis, spinal cord injury, autoimmune arthritis." (PMID 30728014, 2019).
scrapie (1 paper, 2020). A fatal disease of the nervous system in sheep and goats, characterized by pruritus, debility, and locomotor incoordination. "Protein BAMBI displayed an upregulation in the CSF of scrapie sheep at the clinical stage (2465 ± 174 pg/mL) compared to those at the preclinical stage (2103 ± 132 pg/mL, p < 0.01) and to control sheep (2114 ± 84 pg/mL, p < 0.01)." (PMID 32370154, 2020). "Immunostaining of BAMBI displayed a homogeneous intranuclear pattern in both neurons and glial cells in all brain areas of scrapie and control sheep." (PMID 32370154, 2020). "The upregulation observed in our study in scrapie medullae at the transcript level, the increment of BAMBI immunostaining in several CNS areas of both scrapie models and its positive correlation with scrapie-related lesions suggest a role of this protein in prion neuropathology." (PMID 32370154, 2020). "The expression and distribution of proteins encoded by differentially expressed genes, i.e., BAMBI (BMP (bone morphogenetic protein) and activin membrane-bound inhibitor) and CHGA (chromogranin A), were subsequently evaluated in the CNS of scrapie-affected sheep and transgenic mice." (PMID 32370154, 2020). "Using natural ovine scrapie, our study certainly suggests that BAMBI and CHGA could play a relevant role in TSE neuropathology in vivo and may be involved in the characteristic neuroinflammatory response associated to these disorders." (PMID 32370154, 2020). "On the contrary, BAMBI was upregulated in scrapie medullae (p < 0.05)." (PMID 32370154, 2020). "Dysregulated genes (BAMBI and CHGA) were further analysed in a transgenic murine model (Tg338) of scrapie, and their protein distribution was determined using immunohistochemistry and Western blot." (PMID 32370154, 2020). "After Bonferroni correction for multiple tests, a significant difference of BAMBI staining was observed in DCN (p < 0.05) between controls and scrapie-infected mice at the clinical stage of the disease." (PMID 32370154, 2020). "Similar to BAMBI, the staining of CHGA was stronger in scrapie brains, being significantly higher in Fc (p = 0.015), Cbl (p = 0.004) and Mo (p = 0.031)." (PMID 32370154, 2020). "Finally, although both analysed proteins, BAMBI and CHGA, were overexpressed in the CNS of scrapie-infected animals, only BAMBI levels were significantly upregulated in the CSF of scrapie sheep at the clinical stage." (PMID 32370154, 2020). "BAMBI and CHGA distribution was not identical but the scores of these proteins were always higher in scrapie animals." (PMID 32370154, 2020).
yolk sac tumours (1 paper, 2023). "Intriguingly, SOX17 and BAMBI, implicated in yolk sac tumours, were increased in TCam-2 cells by both activin A and BMP4 exposure at 48 h." (PMID 37048077, 2023).
tumor (34 papers, 2010 to 2026). "The results showed that BAMBI was associated with tumor proliferation, epithelial–mesenchymal transition (EMT) markers, glycolysis, fatty acid biosynthesis and degradation pathways, and immune checkpoint regulation in HCC." (PMID 39684424, 2024). "In prior literature, implicated overlapping genes, including WASF3, EDNRB, SOX10, BAMBI have been implicated in processes including tumor progression, migration, and invasion." (PMID 38857306, 2024). "The gene-expression signature of these ten autophagy-related genes, with one of them being BAMBI, was positively associated with an advanced tumor stage." (PMID 36834884, 2023). "In conclusion, the data presented here provide a novel mechanism by which ctHBx might contribute to strong hepato-oncogenesis via the loss of tumor-suppressive β-catenin/BAMBI signaling." (PMID 27909336, 2016). "Finally, the hypothesis that BAMBI may play a significant role in endothelial function might even extend to the reported association of BAMBI expression with tumor progression and metastasis." (PMID 20886049, 2010). "In the GOYA cohort, high expression of BAMBI correlated with diminished CD4+ T cell enrichment in tumour tissues, a trend mirrored by TGFB1." (PMID 41492119, 2026). "Deeper investigations into commonly overexpressed genes, including ASPN, STK3 and BAMBI, via immunohistochemistry revealed novel findings on cellular protein expression in canine tumours." (PMID 40566602, 2025). "The high mRNA expression of BAMBI in tumors with overexpression of the hepatic stem cell marker, the epithelial cell adhesion molecule, indicated a tumor-promoting function of BAMBI." (PMID 39457709, 2024). "BAMBI expression tended to increase as tumor grade increased from 1 to 4 in patients with HCC but decreased as tumor grade increased in patients with KIRC." (PMID 39684424, 2024). "Immunoblot analysis revealed reduced BAMBI protein in non-tumor tissues of patients with HCV in comparison to patients with HBV and normal human liver tissues." (PMID 39457709, 2024). "In patients with tumor grades 1 to 4, BAMBI expression levels were significantly higher in HCC and lower in KIRC compared with the levels in the corresponding normal tissues." (PMID 39684424, 2024). "Xenotransplantation of the BAMBI-expressing HCC cells also revealed a tumor-suppressive role of BAMBI." (PMID 39457709, 2024). "The results showed that BAMBI was positively correlated with tumor proliferation, EMT markers, MYC targets, and cellular response to hypoxia in HCC; it was negatively correlated with glycolysis/gluconeogenesis and fatty acid degradation pathways." (PMID 39684424, 2024). "Currently, one study from China has analyzed BAMBI protein in a large cohort of patients with HCC and found that BAMBI protein is highly elevated in HCC tissue compared to non-tumor liver tissue with very low BAMBI protein levels." (PMID 39457709, 2024). "A study showing that C-terminal-truncated HBV X, which contributes to carcinogenesis, downregulated BAMBI, providing evidence for a tumor-protective role of BAMBI." (PMID 39457709, 2024). "We also sought to elucidate the mechanisms by which BAMBI contributes to tumor growth and progression." (PMID 39684424, 2024). "Further analysis revealed that BAMBI was strongly correlated with tumor proliferation, EMT markers, MYC targets, cellular response to hypoxia, glycolysis/gluconeogenesis, fatty acid degradation pathways, as well as regulating immune checkpoints in HCC." (PMID 39684424, 2024). "Understanding the dual role of BAMBI in tumor biology is crucial for developing new treatment strategies and improving patient outcomes." (PMID 39684424, 2024). "Consistently, we observed a lower level of tumor-infiltrating MDSCs in mice transferred with BAMBI-overexpressing BMCs with IR and higher levels in those transferred with Bambi-KD BMCs." (PMID 38099498, 2023).